ADRA1A (adrenoceptor alpha 1A)
Description:
Alpha-1 adrenergic receptors are G protein-coupled receptors for catecholamines that signal through the G(q) family of G proteins, including G(q) and G(11). Upon activation, they stimulate the phosphatidylinositol-calcium second messenger pathway, leading to calcium release from intracellular stores and activation of protein kinase C. ADRA1A binds the catecholamine ligands norepinephrine and epinephrine. Can also couple to G(14) protein (By similarity). Nuclear ADRA1A forms heterooligomers with ADRA1B to regulate phenylephrine(PE)-stimulated ERK signaling in cardiac myocytes. At the plasma membrane, ADRA1A interacts with CAVIN4/MURC to regulates ERK activation in cardiomyocytes, contributing to the regulation of cardiac hypertrophy. Additionally, functions as a vasopressor in resistance arteries and plays a role in maintaining normal arterial blood pressure (By similarity).
Synonyms: ADRA1C; ADRA1L1; ALPHA1AAR
Tractability: Small molecule: an approved drug acts on it; a structure with a bound ligand is known; a high-quality ligand is known; it belongs to a druggable protein family. Antibody: UniProt places it where antibodies can reach, with high confidence; its Gene Ontology location is reachable by antibodies, with high confidence; UniProt predicts a signal peptide or a membrane-spanning region. PROTAC: ubiquitination databases record sites on it; a small molecule that binds it is known. Other modalities: an approved drug acts on it.
Target class: Small molecule receptor (family A GPCR); Adrenergic receptor; Monoamine receptor; Membrane receptor; Family A G protein-coupled receptor
Chemical probes: CHEMBL448620, PD134462, TERAZOSIN
Safety:
Unwanted effects reported when the protein is acted on. In parentheses: how it was acted on, where the effect was seen, and who reports it.
orthostatic hypotension (Bowes et al. (2012): inhibition, cardiovascular system, central nervous system, gastrointestinal; Lynch et al. (2017): inhibition, acute dosing, cardiovascular; Urban et al. (2012): inhibition, cardiovascular system, gastrointestinal)
cardiac positive ionotropy (Urban et al. (2012): activation, cardiovascular system, gastrointestinal; Bowes et al. (2012): activation, cardiovascular system, central nervous system, gastrointestinal)
dizziness (Lynch et al. (2017): inhibition, acute dosing, cardiovascular; Bowes et al. (2012): inhibition, cardiovascular system, central nervous system, gastrointestinal)
increased blood pressure (Lynch et al. (2017): activation, acute dosing, cardiovascular; Bowes et al. (2012): activation, cardiovascular system, central nervous system, gastrointestinal)
increased heart rate (Bowes et al. (2012): inhibition, cardiovascular system, central nervous system, gastrointestinal; Lynch et al. (2017): inhibition, acute dosing, cardiovascular)
arrhythmia (activation; cardiovascular system, gastrointestinal; source: Urban et al. (2012))
blood pressure events (inhibition; cardiovascular system, gastrointestinal; source: Urban et al. (2012))
cardiac arrhythmia (activation, acute dosing; cardiovascular; source: Lynch et al. (2017))
chronic heart failure (inhibition, acute dosing; cardiovascular; source: Lynch et al. (2017))
decreased blood pressure (inhibition, acute dosing; cardiovascular; source: Lynch et al. (2017))
decreased insulin release (activation; cardiovascular system, central nervous system, gastrointestinal; source: Bowes et al. (2012))
decreased smooth muscle tone (inhibition; cardiovascular system, central nervous system, gastrointestinal; source: Bowes et al. (2012))
impact on various aspects of sexual function (inhibition; cardiovascular system, central nervous system, gastrointestinal; source: Bowes et al. (2012))
increased cardiac contractility (activation, acute dosing; cardiovascular; source: Lynch et al. (2017))
increased pupil diameter (activation, acute dosing; cardiovascular; source: Lynch et al. (2017))
mydriasis (activation; cardiovascular system, central nervous system, gastrointestinal; source: Bowes et al. (2012))
potential for arrhythmia (activation; cardiovascular system, central nervous system, gastrointestinal; source: Bowes et al. (2012))
retrograde ejaculation (inhibition, acute dosing; cardiovascular; source: Lynch et al. (2017))
sexual function (inhibition; cardiovascular system, gastrointestinal; source: Urban et al. (2012))
smooth muscle contraction (activation; cardiovascular system, central nervous system, gastrointestinal; source: Bowes et al. (2012))
smooth-muscle contraction (prostate in particular, effects on the lower urinary tract) (activation; cardiovascular system, gastrointestinal; source: Urban et al. (2012))
vascular hypertrophy (activation, acute dosing; cardiovascular; source: Lynch et al. (2017))
Gene: Protein-coding gene on chromosome 8 (26,748,150 to 26,867,278, reverse strand). Ensembl gene ENSG00000120907.
Subcellular location: Nucleus membrane; Cell membrane; Cytoplasm; Membrane, caveola
Subcellular location (Human Protein Atlas): Cytosol; Nucleoplasm; Vesicles
Pathways (Reactome):
Signal Transduction: Adrenoceptors; G alpha (12/13) signalling events; G alpha (q) signalling events
Gene Ontology:
Molecular function: alpha1-adrenergic receptor activity; protein binding; protein heterodimerization activity; adrenergic receptor activity; G protein-coupled receptor activity
Biological process: phospholipase C-activating G protein-coupled receptor signaling pathway; positive regulation of cardiac muscle hypertrophy; positive regulation of MAPK cascade; adenylate cyclase-activating adrenergic receptor signaling pathway; apoptotic process; cell-cell signaling; G protein-coupled receptor signaling pathway; intracellular signal transduction; negative regulation of cell population proliferation; neuron-glial cell signaling; norepinephrine-epinephrine vasoconstriction involved in regulation of systemic arterial blood pressure; phospholipase C-activating adrenergic receptor signaling pathway; positive regulation of action potential; positive regulation of cardiac muscle contraction; positive regulation of cytosolic calcium ion concentration; positive regulation of ERK1 and ERK2 cascade; positive regulation of synaptic transmission, GABAergic; positive regulation of vasoconstriction; response to hormone; response to xenobiotic stimulus; signal transduction; smooth muscle contraction; pilomotor reflex; positive regulation of smooth muscle contraction; regulation of blood pressure; and 3 more
Cellular component: cytoplasm; cytosol; nuclear membrane; nucleus; plasma membrane; caveola; membrane
Genetic constraint (gnomAD): Loss-of-function variants: 31 observed, 31.16 expected, observed/expected ratio (o/e) 1, 90% interval 0.75 to 1.34. The upper end of that interval is the gene's LOEUF score, 1.34, which puts it in group 5 of 6, group 1 being the genes least tolerant of losing a copy. Missense variants: 619 observed, 638.97 expected, observed/expected ratio (o/e) 0.97, 90% interval 0.91 to 1.03. Synonymous variants: 311 observed, 275.48 expected, observed/expected ratio (o/e) 1.13, 90% interval 1.03 to 1.24.
Homologues: Orthologues: rabbit ADRA1A (94% identical), guinea pig ADRA1A (93% identical), dog ADRA1A (93% identical), pig ADRA1A (93% identical), chimpanzee ADRA1A (92% identical), mouse Adra1a (92% identical), macaque ADRA1A (91% identical), rat Adra1a (87% identical), tropical clawed frog adra1a (68% identical), zebrafish adra1aa (59% identical), Caenorhabditis elegans ser-5 (24% identical). Paralogues in human: ADRA1B (49% identical), ADRA1D (46% identical), ADRB1 (28% identical), ADRB3 (27% identical), ADRA2A (26% identical), ADRA2C (26% identical), ADRA2B (26% identical), DRD2 (26% identical), ADRB2 (25% identical), GPR101 (21% identical), OR56A3 (12% identical), OR56A4 (12% identical), and 6 more.
Diseases named in the same sentence as ADRA1A in open-access papers:
ADRA1A is named in the same sentence as 61 diseases in open-access papers, as found by Europe PMC text mining. Sharing a sentence is not in itself a finding about the gene and the disease. The quoted sentences say what the papers report.
Hypertension (9 papers, 2008 to 2025). The presence of chronic increased pressure in the systemic arterial system. "Among these, ADRA1A is the predominant α1-adrenergic receptor subtype in the adipose tissue vasculature of obese individuals and has been implicated in regulating vascular tone and obesity-driven hypertension." (PMID 40149398, 2025). "The isoforms (e.g., ADRA1A) was associated with hypertension in patients." (PMID 36134646, 2023). "Present data suggested that, although ADRA1A Cys allele may have a discrete effect in individuals from the general population, it might become a relevant marker of the hypertension risk in individuals younger than 45-years." (PMID 19105822, 2008). "ADRA1 remained associated with hypertension (Ppath<0.03) and DBP (Ppath<0.01) even when the ADRA1 receptor genes (ADRA1A, ADRA1B, ADRA1D) were removed from the model, indicating multiple genes within the pathway were responsible for the observed association." (PMID 22615923, 2012). "Of the three alpha 1 adrenergic receptor isoforms (ADRA1A, ADRA1B, ADRA1D), ADRA1B showed the strongest association with hypertension (Pgene<0.005), DBP (Pgene<0.02), and SBP (Pgene<0.02)." (PMID 22615923, 2012). "We assayed for several transcripts involved in the activation (Hctr1), synthesis (Th, Nts), and downstream signaling (Adra1a, Abrb1) of catecholamines to gain a deeper understanding of the sex-specific organ differences of sympathetic pathways in the development of hypertension." (PMID 39514592, 2024). "Moreover, downregulation of Adra1a expression or its reduced activity may be responsible for cardiac hypertrophy and heart failure in mice that develop hypertension due to increased Ang II during pregnancy." (PMID 36736425, 2023). "Furthermore, when all SNPs within the ADRA1 receptor genes (ADRA1A, ADRA1B, ADRA1D) were removed from the model, the ADRA1 pathway remained associated with hypertension and DBP, suggesting that the observed pathway association was driven by genetic variants in several genes." (PMID 22615923, 2012).
cardiac hypertrophy (3 papers, 2017 to 2023). "In contrast to the upregulated genes, excessively increased Ang II levels caused a significant decrease in Adra1a expression in hypertensive pregnancy, which enhanced cardiac hypertrophy." (PMID 36736425, 2023). "Furthermore, we found that Adra1a-deficient PAH mice exhibited more severe cardiac hypertrophy than PAH mice." (PMID 36736425, 2023). "Notably, Ang II-induced cardiac hypertrophy was significantly increased by Adra1a deficiency during pregnancy." (PMID 36736425, 2023). "Our study suggests that Adra1a levels are regulated by renin-angiotensin system and that changes in Adra1a expression are involved in progressive cardiac hypertrophy in PAH mice." (PMID 36736425, 2023). "This study also showed that RAS pathway inhibition has therapeutic potential in cardiac hypertrophy through its ability to reduce the alteration of Adra1a expression in patients with HDP." (PMID 36736425, 2023). "Furthermore, we showed that reduced Adra1a expression is critical for Ang II-induced cardiac hypertrophy in PAH mice." (PMID 36736425, 2023). "Therefore, our results suggest that the RAS pathway-derived ADRA1A regulatory pathway is involved in pathological cardiac hypertrophy during pregnancy." (PMID 36736425, 2023). "Thus, we focused on the relationship between Ang II and Adra1a expression in cardiac hypertrophy and investigated whether elevated Ang II levels regulate Adra1a mRNA levels during pregnancy." (PMID 36736425, 2023). "Consistent with previous reports, we observed that re-expression of Adra1a in Mrps5cKO hearts did not induce cardiac hypertrophy." (PMID 36949106, 2023).
heart failure (3 papers, 2019 to 2023). Inability of the heart to pump blood at an adequate rate to meet tissue metabolic requirements. "Meanwhile diabetes can cause pathological cardiac remodeling and heart failure by elevating the protein expression and activity of ADAM17, affecting ADRA1A regulation and AMPK signaling, and increasing myocardial fibrosis and cardiomyocyte apoptosis." (PMID 36699083, 2022). "However, activation of ADRA1A by highly selective agonists protects against cardiotoxicity and heart failure in animal models such as doxorubicin- and bleomycin-stimulated mice." (PMID 36736425, 2023).
hepatocellular carcinoma (3 papers, 2022 to 2024). A malignant tumor that arises from hepatocytes. "Previous studies have demonstrated that ADRA1A plays a crucial role in various cancer progresses, including hepatocellular carcinoma, gastric carcinoma, lung cancer and hysterocarcinoma." (PMID 36054420, 2022). "Promoter aberrant hypermethylation of ADRA1A might contribute to the initiation of hepatocellular carcinoma." (PMID 36611170, 2023).
depression (2 papers, 2021 to 2022). "Other targets such as ADRA1A, ADRB1, and SLC6A4 modify the occurrence of depression and other mental diseases." (PMID 35800440, 2022).
dyslipidemia (2 papers, 2008 to 2017). "Moreover, ADRA1A gene expression was positively associated with the cumulative number of metabolic syndrome components, with the presence of Arg347 allele of ADRA1A identified as a risk factor for metabolic abnormalities." (PMID 28367128, 2017).
epilepsy (2 papers, 2013 to 2021). A brain disorder characterized by episodes of abnormally increased neuronal discharge resulting in transient episodes of sensory or motor neurological dysfunction, or psychic dysfunction. "Moreover, ADRA1A and Galanin were shown to inhibit seizure responses in animal models of epilepsy." (PMID 23418513, 2013).
fibromyalgia (2 papers, 2018 to 2022). A chronic disorder of unknown etiology characterized by pain, stiffness, and tenderness in the muscles of neck, shoulders, back, hips, arms, and legs. "In two subsamples (from Spain and Mexico), a previous study analysed associations of 4 ADRA1A SNPs, showing that only rs1383914 was associated with an increased risk of fibromyalgia susceptibility in the Spanish sample." (PMID 29486785, 2018). "Although RNA-seq showed that TRPV1 was the most highly upregulated gene after J2H-1702 treatment of TGF-β1-induced LX2 cells, we saw no significant change in the expression of TRPV1 and ADRA1A, both of which are fibromyalgia-related genes, following J2H-1702 treatment in TGF-β1-treated LX2 cells." (PMID 36446766, 2022).
generalized anxiety disorder (2 papers, 2021 to 2025). An anxiety disorder characterized by excessive and difficult-to-control worry about a number of life situations. "Moreover, adrenergic receptors variants (including ADRA1A) were recently identified as the susceptibility factor for GAD (generalized anxiety disorders)." (PMID 34834117, 2021). "As ADRA1A has also been reported to be associated with ADHD, SZ and generalized anxiety disorder by GWAS, a detailed study of Adra1a with respect to its contribution to the DKO phenotypes is warranted in the future." (PMID 39875098, 2025). "Both GABRB2 and ADRA1A have been reported to be associated with several psychiatric disorders: the former with SZ, BP, FTD and ASD and the latter with attention deficit hyperactivity disorder (ADHD), SZ and generalized anxiety disorder (GAD), thus making them good candidates for the DKO phenotypes." (PMID 39875098, 2025).
hypertrophic cardiomyopathy (2 papers, 2021 to 2023). A condition in which the myocardium is hypertrophied without an obvious cause. "To this end, we conducted gene enrichment analysis, and observed stronger enrichments of upregulated genes involved in hypertrophic cardiomyopathy (ADRA1A, TNNI3, MYL2) and cardiac muscle contraction (CACNA1C, CASQ2, CAMK2B)." (PMID 37084237, 2023).
lung carcinoma (2 papers, 2022 to 2024). "On the other hand, circ_0080608, which is under-expressed in tumor tissue, has been associated with suppressing lung cancer progression by regulating the miR-661/ADRA1A (Adrenergic Receptor Alpha 1A) pathway." (PMID 38501058, 2024).
Obesity (2 papers, 2022 to 2025). Accumulation of substantial excess body fat. "For instance, the alpha-1A adrenergic receptor (ADRA1A) gene has been linked to cardiovascular risk factors such as obesity and hypertension, and a positive connection has been observed between the presence of the Arg347 allele of ADRA1A and the total number of metabolic syndrome (MetS) components." (PMID 36362270, 2022).
prostate carcinoma (2 papers, 2024 to 2025). A carcinoma that arises from epithelial cells of the prostate gland. "Anti-ADRA1A autoantibodies have been described in prostate cancer patients and exert functional activity in in vitro models supporting carcinogenesis by excessive receptor stimulation." (PMID 40768895, 2025).
Alzheimer disease (1 paper, 2020). A progressive, neurodegenerative disease characterized by loss of function and death of nerve cells in several areas of the brain leading to loss of cognitive function such as memory and language. "Genes identified by our method suggest putative roles of several biological processes in Alzheimer’s disease, including mitochondrial dysfunction (indicated by UQCR11, MTCH2 and TMEM135), cholesterol transportation (indicated by TMEM135 and OSBP), and neuron activity (indicated by ADRA1A)." (PMID 33137096, 2020).
Anxiety (1 paper, 2023). Intense feelings of nervousness, tension, or panic often arise in response to interpersonal stresses. "The mechanisms mediating the effect ofADRA1A in behavior regulation are poorly understood, butit is known that long-term ADRA1A stimulation mitigatesdepression-like behavior and anxiety, and tricyclic antidepressantsincrease the ADRA1A receptor density in theforebrain of rodents." (PMID 38213464, 2023).
Arrhythmia (1 paper, 2021). Any cardiac rhythm other than the normal sinus rhythm. "The PPI k-means classification results suggested that 25 genes, iADORA1, ADORA2B, ADRA1A, ADRA1B, and ADRA1D, play a more important role in arrhythmia pathology and PRP treatment." (PMID 34393777, 2021).
asthma (1 paper, 2022). "According to RNA-Seq results for HASM cells derived from age- and sex-matched fatal asthma or nonasthma lung donors, both the ADRA1A and ADRA1B genes (encoding α1AR subtypes A and B) were expressed." (PMID 35787178, 2022).
cardiomyopathy (1 paper, 2023). A disease of the heart muscle or myocardium proper. "Upregulated DEGs were associated with pro-fibrotic signaling, such as TGF-β signaling-associated genes (TGFB1, LTBP1, ANKRD1) and other cardiomyopathy-related signaling, such as the MAPK cascade (ADRA1A, EGR1, IL6R)." (PMID 37084237, 2023).
cervical cancer (1 paper, 2024). A primary or metastatic malignant neoplasm involving the cervix. "Our results, combined with previous knowledge, pinpoint ADRA1A as a potential tumor suppressor gene in various tissues and indicate a possible role in cervical cancer development that has not yet been described." (PMID 39766077, 2024).
cholangiocarcinoma (1 paper, 2024). A carcinoma that arises from the intrahepatic biliary tree (intrahepatic cholangiocarcinoma) or from the junction, or adjacent to the junction, of the right and left hepatic ducts (hilar cholangiocarcinoma). "TCGA-CHOL (Cholangiocarcinoma) shows upregulations of HTR3A (35.1-fold) and GPR35 (G Protein-Coupled Receptor 35) (33.9-fold), with downregulations in ADRA1A (−74.3-fold) and ESR1 (Estrogen Receptor 1) (−43.2-fold)." (PMID 39766077, 2024).
dry eyes (1 paper, 2022). "In PCS/ME/CFS patients, the secretomotor symptoms (dry eyes, dry mouth) correlated negatively with levels of AABs against AGTR1, EDNRA, ADRA1A, ADRB1/2, and CHRM3 (black bars)." (PMID 36238301, 2022). "Similarly, the negative correlation of the secretomotor symptoms (dry eyes, dry mouth) with levels of AAB against vasoregulatory receptors AGTR1, EDNRA, ADRA1A, ADRB1/2, and CHRM3 indicate a vascular mechanism." (PMID 36238301, 2022).